LINC02037 (long independently transcribed non-coding RNA 2037)
Gene: Long non-coding RNA gene on chromosome 3 (194,237,180 to 194,261,526, forward strand). Ensembl gene ENSG00000238097.
Diseases named in the same sentence as LINC02037 in open-access papers:
LINC02037 is named in the same sentence as 3 diseases in open-access papers, as found by Europe PMC text mining. Sharing a sentence is not in itself a finding about the gene and the disease. The quoted sentences say what the papers report.
cancer (1 paper, 2019). A tumor composed of atypical neoplastic, often pleomorphic cells that invade other tissues. "So far, no studies have reported any association between LINC00377, LINC00536, LINC01224, and LINC02037, and cancer." (PMID 31850229, 2019).
LINC02037 also shares sentences with these, for which no sentence is quoted: breast carcinoma (2 papers); colorectal cancer (1).